ZNRF3 (zinc and ring finger 3)
Description:
E3 ubiquitin-protein ligase that acts as a negative regulator of the Wnt signaling pathway by mediating the ubiquitination and subsequent degradation of Wnt receptor complex components Frizzled and LRP6. Acts on both canonical and non-canonical Wnt signaling pathway. Acts as a tumor suppressor in the intestinal stem cell zone by inhibiting the Wnt signaling pathway, thereby restricting the size of the intestinal stem cell zone. Along with RSPO2 and RNF43, constitutes a master switch that governs limb specification (By similarity).
Synonyms: KIAA1133; RNF203; BK747E2.3; FLJ22057
Tractability: Small molecule: a structure with a bound ligand is known. Antibody: UniProt places it where antibodies can reach, with high confidence; its Gene Ontology location is reachable by antibodies, with high confidence; UniProt predicts a signal peptide or a membrane-spanning region. PROTAC: ubiquitination databases record sites on it.
Gene: Protein-coding gene on chromosome 22 (28,883,565 to 29,057,488, forward strand). Ensembl gene ENSG00000183579.
Subcellular location: Cell membrane
Subcellular location (Human Protein Atlas): Golgi apparatus
Pathways (Reactome):
Signal Transduction: Regulation of FZD by ubiquitination
Gene Ontology:
Molecular function: frizzled binding; protein binding; ubiquitin-protein transferase activity; ubiquitin protein ligase activity
Biological process: negative regulation of canonical Wnt signaling pathway; negative regulation of non-canonical Wnt signaling pathway; protein ubiquitination; ubiquitin-dependent protein catabolic process; Wnt receptor catabolic process; limb development; stem cell proliferation; negative regulation of Wnt signaling pathway; regulation of canonical Wnt signaling pathway; regulation of non-canonical Wnt signaling pathway; regulation of Wnt signaling pathway, planar cell polarity pathway
Cellular component: plasma membrane
Genetic constraint (gnomAD): Loss-of-function variants: 22 observed, 62.46 expected, observed/expected ratio (o/e) 0.35, 90% interval 0.25 to 0.5. The synonymous counts are far from expectation, so gnomAD's model fits this gene poorly and the ratio says little. Missense variants: 1,169 observed, 1,208.8 expected, observed/expected ratio (o/e) 0.97, 90% interval 0.92 to 1.01. Synonymous variants: 610 observed, 513.01 expected, observed/expected ratio (o/e) 1.19, 90% interval 1.11 to 1.27.
Homologues: Orthologues: macaque ZNRF3 (98% identical), chimpanzee ZNRF3 (91% identical), dog ZNRF3 (90% identical), pig ZNRF3 (87% identical), mouse Znrf3 (85% identical), rat Znrf3 (85% identical), guinea pig ZNRF3 (80% identical), rabbit ZNRF3 (74% identical), zebrafish znrf3 (59% identical), tropical clawed frog znrf3 (58% identical). Paralogues in human: RNF43 (24% identical).
Diseases named in the same sentence as ZNRF3 in open-access papers:
ZNRF3 is named in the same sentence as 64 diseases in open-access papers, as found by Europe PMC text mining. Sharing a sentence is not in itself a finding about the gene and the disease. The quoted sentences say what the papers report.
colorectal cancer (16 papers, 2016 to 2025). A primary or metastatic malignant neoplasm that affects the colon or rectum. "Mutations leading to a defective ZNRF3 protein were identified in several tumor types, but most frequently in colorectal cancers enriched for a mismatch repair defect, BRAF-V600E mutation and right-sided tumor location." (PMID 39674817, 2025). "Several RNF43/ZNRF3 genetic variants have been detected in human malignancies, however recent work in colorectal cancer has highlighted the need to determine which variants are pathogenic." (PMID 35204808, 2022). "We analysed RNF43 and ZNRF3 for mutation, copy number variation and expression in a large number of colorectal cancers stratified for molecular subtype." (PMID 27661107, 2016). "This study provides a comprehensive analysis of RNF43 and ZNRF3 in cohorts of colorectal cancers stratified by BRAF mutation and MSI status." (PMID 27661107, 2016). "The RNF43 and ZNRF3 mutant colorectal cancer cell lines were all MSI, and all harbour a mutation within the EGFR-MAPK signalling pathway." (PMID 27661107, 2016). "Finally, we show that defective ZNRF3 variants are most common in mismatch repair-defective colorectal cancers, where they co-occur with other gene mutations expected to lead to modest β-catenin activation." (PMID 39674817, 2025). "Thus, in colorectal cancer ZNRF3 mutations are often accompanied by other gene mutations that are expected to weakly increase β-catenin signaling." (PMID 39674817, 2025). "To test the effect of RNF43 KO, we utilized HT29, a colorectal cancer cell line that expresses WT RNF43 at a high level but minimal ZNRF3." (PMID 38260423, 2024). "In colorectal cancer (CRC), ZNRF3 and RNF43 mutations occur frequently and have been mainly associated with the potentiation of WNT signaling." (PMID 38260423, 2024). "Subsequently, we investigated the impact of depleting ZNRF3 or RNF43 on EGFR clearance at the cell surface in mouse embryonic fibroblasts (MEFs) and human cancer cell lines including APC-mutated colorectal cancer cells." (PMID 38260423, 2024). "Membrane-bound E3 ubiquitin ligases RNF43 and ZNRF3 are overexpressed in colorectal cancer, and can be repurposed using proteolysis-targeting antibodies (PROTABs) to selectively degrade cell-surface receptors in tumours." (PMID 36131013, 2022). "RNF43 and ZNRF3 are regarded as tumor suppressors in multiple cancer types, such as gastric, ovarian, pancreatic, endometrial, and colorectal cancers." (PMID 35204808, 2022). "Mainly, miR-146a-5p promoted the growth of human osteosarcoma by targeting the ZNRF3/GSK3β/β-catenin pathway and enhanced the migration and invasion of human colorectal cancer cells by targeting the carboxypeptidase M/src-FAK pathway." (PMID 34051870, 2021). "For instance, enforced expression of ZNRF3 inhibited cell proliferation and facilitated cell apoptosis in colorectal cancer." (PMID 34657141, 2021). "ZNRF3 as a member of E3 ubiquitin ligases family is downregulated in gastric cancer and papillary thyroid carcinoma and colorectal cancer, and inhibits cell growth and invasion and induces apoptosis via regulation of the Wnt/β-catenin pathway." (PMID 29088784, 2017). "Interestingly, alternative ubiquitination targets of RNF43 and homologous ligase ZNRF3 at the plasma membrane include EGFR, which is deregulated by pathogenic mutations in a sub-set of CDX2-suppressed colorectal cancers." (PMID 39452477, 2024). "Functionally, it was shown that RNF43 as well as ZNRF3 mutant colorectal cancers may be Wnt ligand dependent and that inhibition of the Wnt signal by targeting Porcupine may facilitate decreased growth of a proportion of MSI serrated pathway cancers." (PMID 27661107, 2016). "Ten colorectal cancer cell lines were analysed for presence of an RNF43 and ZNRF3 mutation." (PMID 27661107, 2016).
colorectal cancer (continued). "Mutation of ZNRF3, a Wnt signaling suppressor, is often found in adrenocortical carcinoma, while AXIN2 mutations induce a predisposition to colorectal cancer, its mutations are detected in colorectal cancer, finally leading to the accumulation of beta-catenin in the nuclei." (PMID 34488905, 2021). "Focusing on zinc- and ring finger 3 (ZNRF3), a Wnt-responsive ligase, we show that this approach can enable colorectal cancer-specific degradation." (PMID 36131013, 2022). "Besides frequent deletions in ACC, ZNRF3 and RNF43 are also important tumor suppressors in the more commonly occurring colorectal cancer (CRC); thus, we next analyzed the TCGA colorectal adenocarcinoma (n=629) and CPTAC colon adenocarcinoma (n=110) datasets." (PMID 38260423, 2024). "Additionally, the POP112 line did not harbour mutations or deep amplifications or deletions in the WNT pathway members defined as colorectal cancer drivers APC, AXIN1, AXIN2, CTNNB1, GSK3B or RNF43, and only a shallow deletion in ZNRF3." (PMID 38324534, 2024). "However, hyperactivation of Wnt signaling in colorectal cancer results in an elevated expression of RNF43 and ZNRF3." (PMID 37592990, 2023). "As for ZNRF3, a higher expression of ZNRF3 was found to be related with a better survival in colorectal carcinoma 48, while its role in ccRCC has not been elucidated." (PMID 34093816, 2021). "Furthermore, we validated ZNRF3/RNF43-EGFR signaling in prostate cancer, one of the several other tumors in patients besides colorectal cancer that showed a negative correlation ZNRF3/RNF43 mRNA and EGFR protein levels." (PMID 38260423, 2024). "Our work began with computational studies of public data identifying a strong negative correlation between ZNRF3/RNF43 mRNA levels and EGFR protein expression in datasets of human adrenocortical carcinomas and colorectal cancers." (PMID 38260423, 2024).
adrenocortical carcinomas (10 papers, 2015 to 2025). "Adrenocortical carcinoma (ACC) is the only cancer type with a frequent mutation of ZNRF3 at 21.0%." (PMID 27338477, 2016). "A similar explanation may also apply to ZNRF3-mutant cancers of the endometrium and liver that also often show co-occurrence with other β-catenin activating mutations, while in other cancers such as melanomas and adrenocortical carcinomas the ZNRF3 mutation may be sufficient in itself." (PMID 39674817, 2025). "For instance, ZNRF3 exhibits the highest rate of copy number variations in adrenocortical carcinomas (ACCs), homozygously deleted in approximately 20% of ACCs." (PMID 38260423, 2024). "Given the critical role of ZNRF3 in adrenal hemostasis and its frequent deep deletion in approximately 20% of adrenocortical carcinomas (ACCs), our initial focus was to examine the ACC dataset from TCGA, comprising 92 samples, to identify proteins exhibiting correlations with ZNRF3 mRNA levels." (PMID 38260423, 2024). "Note that this analysis does not account for ZNRF3 deep deletions, which can also lead to ZNRF3 inactivation and are, for example, frequently observed in adrenocortical carcinomas." (PMID 39674817, 2025).
lung carcinoma (6 papers, 2017 to 2023). "Taken together the results support that MET signaling is necessary and sufficient for LRP6 regulation via ZNRF3 and in multiple lung cancer cell lines." (PMID 34590584, 2021). "MiR-93 promotes growth of lung cancer cells via ZNRF3/Wnt/β-catenin axis, and ZNRF3 suppresses the tumorigenesis and metastasis of nasopharyngeal carcinoma cells by inhibition of Wnt/β-catenin signaling." (PMID 29088784, 2017). "Meanwhile, it is able to inactivate ZNRF3, leading to the activation of Wnt signaling, which promote cell proliferation and progression in lung cancer cell lines." (PMID 29156844, 2017). "MiR-93 was also found to target ZNRF3 to promote lung carcinoma growth through Wnt signaling activation." (PMID 27793042, 2017). "Previously, we showed that LGR4 was highly expressed in the lung cancer cell line A549 and RNA-seq expression data showed no expression of LGR5, LGR6, RNF43, and ZNRF3 in A549 cells." (PMID 37402772, 2023).
gastric cancer (5 papers, 2017 to 2023). A primary or metastatic malignant neoplasm involving the stomach. "Indeed, RNF43 and ZNRF3 (which ubiquitinate and stabilise WNT receptors) are found mutated in gastric cancer (RNF43 mutations are frequent, while ZNRF3 mutations are rare)." (PMID 35408991, 2022). "Moreover, ZNRF3 has been identified to be a potential tumor suppressor in several cancers such as gastric cancer, nasopharyngeal cancer, and esophageal squamous cell cancer." (PMID 34657141, 2021).
melanoma (5 papers, 2021 to 2025). A malignant, usually aggressive tumor composed of atypical, neoplastic melanocytes. "Small hairpin RNA (shRNA) and genome‐wide CRISPR‐Cas9‐based genetic screenings in melanoma cells, on the other hand, revealed ZNRF3, NF2 and ARIH1 as genes associated with cisplatin resistance." (PMID 40242936, 2025). "Surprisingly, R2PD1 caused 50% to 90% PD-L1 degradation in melanoma cell lines, which was dependent on ZNRF3/RNF43." (PMID 38638430, 2024). "Causes PD-L1 degradation in melanoma cells, which is dependent on ZNRF3/RNF43." (PMID 38638430, 2024). "Alternatively, RNF43/ZNRF3 KO could affect also canonical Wnt/β-catenin pathway that was shown to drive distinct features of melanoma cells than the ones related to the WNT5A-specific events." (PMID 34702444, 2021). "Lower proliferation of RNF43/ZNRF3 dKO cells can be caused by senescence because these cells have elevated WNT5A pathway activity (i.e.) and WNT5A at the same time causes a senescence-like phenotype of melanoma after exposition to vemurafenib." (PMID 34702444, 2021). "In melanoma, zinc and ring finger 3, an ubiquitin ligase known to be a targeting and negative feedback regulator of Wnt-β catenin signaling enhanced cisplatin resistance in normal and melanoma cells independently of b-catenin." (PMID 38084101, 2023).
pancreatic cancer (5 papers, 2016 to 2025). "Next, we performed qPCR to test the expression of both ZNRF3 RNA variants in colorectal (n = 4), liver (n = 8) and pancreatic cancer (n = 4) cell lines." (PMID 39674817, 2025). "Compared to normal surrounding tissues, the ZnRF3 level in gastric tumor tissues has been lower, and ZnRF3 mutations are prevalent in pancreatic cancer." (PMID 35847032, 2022). "Mutation in RNF43 is more frequent than ZNRF3 and its associated repercussions are pancreatic tumors called intraductal papillary mucinous neoplasm and mucinous cystic neoplasm, colorectal adenocarcinomas, pancreatic cancer, gastric cancer, mucinous ovarian carcinoma, and endometrial carcinomas." (PMID 34535145, 2021). "The strength of this negative feedback regulation is demonstrated by the finding that the knockdown of β?-catenin in a pancreatic cancer line with wild-type ZNRF3 and RNF43 strongly increases the cell surface level of FZD, most likely through down-regulation of endogenous RNF43 and ZNRF3." (PMID 27338477, 2016).
papillary thyroid carcinoma (5 papers, 2015 to 2025). "miR-146 targets Zinc RING finger 3 (ZNRF3), an E3 ubiquitin ligase and an antagonist of Wnt signaling in papillary thyroid carcinoma cells." (PMID 26712794, 2015). "Studies have shown that miR-146b-5p is overexpressed in papillary thyroid carcinoma (PTC) with lymph node metastasis and downregulates the protein expression of zinc RING finger protein 3 (ZNRF3) by directly targeting its 3′-UTR region." (PMID 40530008, 2025).
adenoma (4 papers, 2019 to 2024). A neoplasm arising from the epithelium. "Loss of RNF43 and ZNRF3 induces rapid growth of adenomas, as RNF43 and ZNRF3 target Wnt receptors for degradation by selectively ubiquitinating Fz receptors, thereby attenuating Wnt signaling." (PMID 39329019, 2024). "Inactivation of RNF43 and ZNRF3 induces Wnt-dependent adenoma formation, and these genes are frequently mutated in various human cancers." (PMID 32934222, 2020). "Wnt3 is not essential for ligand-independent intestinal adenomas but is essential for Rnf43;Znrf3-mutant adenomas." (PMID 34788095, 2021). "We analyzed Lef1 expression in Apc-mutant tumors that are ligand independent and in Rnf43;Znrf3-mutant adenomas that are ligand dependent and have a serrated growth pattern." (PMID 34788095, 2021). "Furthermore, Rnf43 and Znrf3 transcripts decreased significantly in the Lef1-deleted adenoma cells concomitantly with decreased expression of Wnt antagonists." (PMID 34788095, 2021). "We show that Lef1 is expressed in Wnt ligand–independent Apc-mutant adenomas, but not in Wnt ligand–dependent Rnf43;Znrf3-mutant intestine." (PMID 34788095, 2021).
colon cancer (4 papers, 2019 to 2024). "Aberrant Wnt/R-spondin/ZNRF3 signaling is implicated in tumorigenesis, where 7% of colon cancer and 31% of serrated adenoma samples harbor RSPO3 gene fusions with the neighboring Protein tyrosine phosphatase receptor-type kappa (PTPRK) gene." (PMID 31934854, 2020). "Previous studies have shown that defects in Wnt signaling and in the activities of PTPRK and ZNRF3 are involved in colon cancer in mammals." (PMID 31934854, 2020). "We then asked how ZNRF3 was related to RNF43 in expression and mutation status in colon cancer as both genes are targets as well as negative regulators of Wnt signaling." (PMID 31811196, 2019). "Remarkably, nearly all BRAF-V600E tumors had low expression of Axin2, RNF43, and ZNRF3, but not vice versa, consistent with previous report of low Wnt signaling in colon tumors with MSI-H BRAF-V600E mutation." (PMID 31811196, 2019). "For example, ZNRF3, a known candidate of PROTAC for colon cancer, has been prioritized as gastrointestinal-specific E3 ligases." (PMID 39395186, 2024). "Furthermore, USP42 stabilizes zinc and ring finger 3 (ZNRF3)/ring finger protein 43 (RNF43) on the cell surface, which plays a role in paracrine Wnt signaling in colon cancer cells." (PMID 35884607, 2022).
nasopharyngeal carcinoma (4 papers, 2017 to 2022). A carcinoma arising from the nasopharyngeal epithelium. "Previously, it has been reported that ZNRF3 has the ability to inhibit the metastasis and tumorigenesis by suppressing the Wnt/β-catenin signalling pathway in nasopharyngeal carcinomas (NPC), hence believed to be a potential molecular target for treatment of NPC." (PMID 29879932, 2018).
prostate carcinoma (4 papers, 2016 to 2024). A carcinoma that arises from epithelial cells of the prostate gland. "Using cBioPortal, we also detected a negative correlation between ZNRF3/RNF43 expression and EGFR protein in multiple other cancer types, including prostate cancer where ZNRF3 or RNF43 is deleted or mutated with a rate of 5%." (PMID 38260423, 2024). "Taken together, these data demonstrate a link between ZNRF3 loss and activation of pathways with well-established links to aggressive prostate cancer." (PMID 34716314, 2021). "Here the authors analyse mutation prevalence in 1844 prostate cancers and show that ZNRF3 loss is enriched in metastatic, castration-resistant prostate cancer and associated with metastasis of localized disease." (PMID 34716314, 2021). "This implicates WNT signaling in the development of aggressive, potentially lethal prostate cancer, consistent with our finding—across multiple independent cohorts—of a link between ZNRF3 loss, WNT pathway activation, and adverse clinical outcomes." (PMID 34716314, 2021). "For example, patients with favorable intermediate risk prostate cancer whose tumors harbor ZNRF3 loss might be triaged out of active surveillance protocols and toward definitive therapy." (PMID 34716314, 2021). "Similarly, the strong upregulation of cell cycle progression, E2F/DREAM, and PRC1/2 pathways in tumors harboring ZNRF3 loss further supports a link between this tumor suppressor and pathways with established links to prostate cancer aggression." (PMID 34716314, 2021). "Of interest, majority of gene loci identified have been reported to be aberrant in prostate cancer biology, such as copy number changes after treatment in RNF43 and ZNRF3 loci." (PMID 27127882, 2016).
Colorectal tumors (3 papers, 2018 to 2021). "Colorectal tumors with mutated RNF43/ZNRF3 or R-spondins 2/3 are sensitive to abrogation of Wnt secretion." (PMID 34849464, 2021). "ZNRF3 is a homolog of RNF43 but truncating mutations are rare in colorectal tumors, potentially reflecting its comparably low mRNA expression in normal colon and colorectal tumors." (PMID 33202731, 2020). "ZNRF3 is also the most frequently deleted gene in ACCs18,19 and is reported to be upregulated in colorectal tumours exhibiting activated Wnt/β-Catenin signaling pathway." (PMID 29872083, 2018).